GPCPD1 (glycerophosphocholine phosphodiesterase 1)
Description:
Shows strong preference for glycerophosphocholine. Displays weak activity toward glycerophosphoethanolamine and no detectable activity toward glycerophosphoglycerol, glycerophosphoserine, or glycerophosphoinosito. May be involved in the negative regulation of skeletal muscle differentiation, independently of its glycerophosphocholine phosphodiesterase activity.
Synonyms: GDE5; KIAA1434; GDPD6; EDI3; PREI4
Tractability: PROTAC: ubiquitination databases record sites on it; its protein half-life has been measured.
Gene: Protein-coding gene on chromosome 20 (5,544,404 to 5,611,045, reverse strand). Ensembl gene ENSG00000125772.
Subcellular location: Cytoplasm
Subcellular location (Human Protein Atlas): Nucleoplasm
Pathways (Reactome):
Metabolism: Hydrolysis of LPC; Hydrolysis of LPE
Gene Ontology:
Molecular function: protein binding; glycerophosphocholine phosphodiesterase activity; carbohydrate binding; phosphoric diester hydrolase activity; starch binding
Biological process: glycerophospholipid catabolic process; lipid metabolic process
Cellular component: cytoplasm
Genetic constraint (gnomAD): Loss-of-function variants: 1 observed, 6.86 expected, observed/expected ratio (o/e) 0.15, 90% interval 0.051 to 0.69. That is too few expected variants to judge how well the gene tolerates losing a copy. Missense variants: 74 observed, 107.37 expected, observed/expected ratio (o/e) 0.69, 90% interval 0.57 to 0.84. Synonymous variants: 41 observed, 39.64 expected, observed/expected ratio (o/e) 1.03, 90% interval 0.81 to 1.34.
Homologues: Orthologues: chimpanzee GPCPD1 (99% identical), macaque GPCPD1 (98% identical), dog GPCPD1 (97% identical), rabbit GPCPD1 (96% identical), pig GPCPD1 (96% identical), guinea pig GPCPD1 (94% identical), mouse Gpcpd1 (93% identical), rat Gpcpd1 (90% identical), tropical clawed frog gpcpd1 (73% identical), zebrafish gpcpd1 (61% identical), Drosophila melanogaster CG2818 (36% identical), Caenorhabditis elegans gpcp-2 (34% identical), and 4 more.
Diseases named in the same sentence as GPCPD1 in open-access papers:
GPCPD1 is named in the same sentence as 23 diseases in open-access papers, as found by Europe PMC text mining. Sharing a sentence is not in itself a finding about the gene and the disease. The quoted sentences say what the papers report.
breast carcinoma (8 papers, 2016 to 2024). "It was reported that doxorubicin decreased the expression of GPCPD1, leading to an ex vivo GPC increase in breast cancer cells." (PMID 35168606, 2022). "EDI3/GPCPD1 regulates migration and invasion of MCF7 breast cancer cells and is a significant prognostic factor in endometrial cancer." (PMID 28393905, 2017).
ovarian carcinoma (3 papers, 2016 to 2024). A malignant neoplasm originating from the surface ovarian epithelium. "GPCPD1 has been reported to promote cell migration, metastasis, adhesion, and diffusion in breast, endometrial, and ovarian cancers." (PMID 36863716, 2023).
sarcopenia (2 papers, 2022 to 2024). Progressive decline in muscle mass due to aging which results in decreased functional capacity of muscles. "In this research, six genetic biomarkers closely associated with sarcopenia, including ARHGAP36, FAM171A1, GPCPD1, MT1X, ZNF415, and RXRG, were identified by WGNCA and LASSO analysis, which were used to future diagnose and screen for sarcopenia." (PMID 36147639, 2022). "Additionally, in patients with sarcopenia, MT1X and ARHGAP36 were upregulated, whereas FAM171A1, GPCPD1, ZNF415 and RXRG, were downregulated, demonstrating high diagnostic accuracy for sarcopenia and potential as predictive markers for screening." (PMID 38337720, 2024). "In the present study, we found that the gene expression of GPCPD1 in muscle samples from patients with sarcopenia was significantly lower than that in normal samples, indicating that GPCPD1 might have the effect of inhibiting muscle atrophy." (PMID 36147639, 2022). "Finally, six hub genes with AUC exceeding 0.9, including GPCPD1, MT1X, ARHGAP36, FAM171A1, ZNF415, and RXRG, were defined as diagnostic biomarkers of sarcopenia." (PMID 36147639, 2022). "Moreover, six hub genes with AUC exceeding 0.9, including ARHGAP36, FAM171A1, GPCPD1, MT1X, ZNF415, and RXRG, were confirmed as diagnostic biomarkers for sarcopenia." (PMID 36147639, 2022). "We found the AUC values of GPCPD1, MT1X, ARHGAP36, FAM171A1, ZNF415, and RXRG on the validation dataset were 0.928, 0.75, 0.978, 0.961, 0.811, and 0.906, indicating that the six biomarkers had high diagnostic accuracy for sarcopenia." (PMID 36147639, 2022). "Compared to normal samples, the expression levels of both MT1X and ARHGAP36 were upregulated in sarcopenia samples, while GPCPD1, FAM171A1, ZNF415, and RXRG showed lower expression in sarcopenia samples." (PMID 36147639, 2022).
Anxiety (1 paper, 2021). Intense feelings of nervousness, tension, or panic often arise in response to interpersonal stresses. "The results showed that Gfap, Rhog, Gnai2, Ppp1r1b, and Uqcrh were specifically dysregulated in the prefrontal cortex of the depression-susceptible group, while Tubb6, Urod, Cul1, Spred1, and Gpcpd1 were specifically dysregulated in the anxiety-susceptible group." (PMID 33627638, 2021).
Glucose intolerance (1 paper, 2024). Glucose intolerance (GI) can be defined as dysglycemia that comprises both prediabetes and diabetes. "Muscle‐specific knockout of Gpcpd1 leads to glucose intolerance." (PMID 39143698, 2024).
Huntington disease (1 paper, 2025). Huntington disease (HD) is a rare neurodegenerative disorder of the central nervous system characterized by unwanted choreatic movements, behavioral and psychiatric disturbances and dementia. "In patients with HD (Huntington’s Disease) and R6/2 mice, both choline and phosphocholine levels decrease in the striatum, while glycerophosphocholine increases, suggesting choline metabolism disruption due to GPCPD1 deficiency, which can be ameliorated by citicoline treatment." (PMID 40278587, 2025).
lung carcinoma (1 paper, 2024). "Therefore, we chose top two of previously unreported potential aging genes (GPCPD1 and TMEM169) to test whether they deregulated in neuroblastoma cell line SH-SY5Y and lung cancer cell line A549 during cell senescence." (PMID 39713269, 2024).
prostate carcinoma (1 paper, 2021). A carcinoma that arises from epithelial cells of the prostate gland. "miRNAs in prostate cancer, the GPCPD1 and NRAS gene, and the same combination of let-7b-5p and let-7i-5p were involved." (PMID 34157951, 2021).
R6 (1 paper, 2024). "Gpcpd1 protein expression in the brains of R6/2 HD mice progressively decreased beginning at the age of 6 weeks, indicating that this process occurs at the early stage of HD, when the phenotype began to manifest and may contribute early neuronal dysfunction." (PMID 39143698, 2024).
cancer (7 papers, 2015 to 2024). A tumor composed of atypical neoplastic, often pleomorphic cells that invade other tissues. "The glycerophosphodiesterase EDI3 (GPCPD1), which hydrolyses glycerophosphocholine to choline and glycerol-3-phosphate, directly influences choline and phospholipid metabolism, and has been linked to cancer-relevant phenotypes in vitro." (PMID 36670508, 2023). "The interactions of downregulated GRHL3 in the control offspring with downregulated GPCPD1 and SNORA41 are indicative of good cancer prognosis." (PMID 28673325, 2017). "GPCPD1 and TDRP genes have not been associated with cancer cell proliferation." (PMID 26310847, 2015).
GPCPD1 also shares sentences with these, for which no sentence is quoted: tumor (6 papers); endometrial carcinoma (2); acute myocardial infarction (1); Atrophy (1); breast tumours (1); depression (1); gastric cancer (1); infection (1); melanoma (1); metastatic cancers (1); neuroblastoma (1); renal carcinoma (1); renal cell carcinoma (1).